IGF1 (insulin like growth factor 1)
Diseases named in the same sentence as IGF1 in open-access papers (continued):
Sharing a sentence is not in itself a finding about the gene and the disease.
Obesity (continued). "For example, the effects of increased levels of insulin and insulin-like growth factor-1 (IGF-1) in obesity have been investigated in primary intestinal epithelial crypts isolated from obese humans." (PMID 34659571, 2021). "Post-feed breast milk IGF-1 levels of mothers with obesity were correlated with infant’s weight for length z-score at 2 months (r −0·476; P = 0·034)." (PMID 34348809, 2021). "This pathway is stimulated by insulin, insulin-like growth factor 1 (IGF-1), exercise, and testosterone, all of which decrease with obesity and aging." (PMID 34676021, 2021). "The impacts of obesity on human physiology include dysregulation of insulin, bioavailable insulin-like growth factor (IGF)-1, adipokines (e." (PMID 33815289, 2021). "Taking into consideration the increased interest in using IGF-1/GH as a therapeutic agent to overcome obesity, we believe that data generated from the two models presented in this review have significant translational implications." (PMID 34685644, 2021). "In turn, the mouse model of high fat diet-induced obesity showed a significant increase in hypothalamic IGF-1 expression as compared to mice fed with a standard chow diet." (PMID 34208601, 2021). "In spite of the marked hyposomatotropism circulating insulin-like growth factor-1 (IGF-1) levels are conflicting in obesity." (PMID 32806629, 2020). "Obesity results in hyperinsulinemia and increased amounts of circulating bioactive insulin-like growth factor-1 (IGF-1), a growth factor that promotes the development of many types of cancer." (PMID 32093338, 2020). "Our data suggest several potential mechanisms including increased local adiposity, increased local inflammation and IGF-1, and polarization of macrophages to an M2 phenotype, providing insight into this obesity enhanced tumor growth in OVX mice." (PMID 33346251, 2020). "Obesity is characterized by reduced growth hormone (GH) secretion, although the insulin-like growth factor-1 (IGF-1) values are controversial." (PMID 32806629, 2020). "In obesity, an increase in IGF-1 has been recorded to lead to an increase in GH binding protein levels, thereby resulting in a lack of suppression of IGF-1." (PMID 32742493, 2020). "The aim of this study was to evaluate the effect of weight loss after bariatric surgery in the GH–IGF-1 axis in extreme obesity, in order to investigate IGF-1 values and the mechanism responsible for the alteration of the GH–IGF-1 axis in obesity." (PMID 32806629, 2020). "Increased secretion of the insulin-like growth factors−1 (IGF-1) in the body and insulin resistance are possible mechanisms by which obesity affects the occurrence of acne." (PMID 33042936, 2020). "Our findings proposed that obesity status should be taken into consideration when featuring the impact of IGF-1 expression on the prognosis of BC patients." (PMID 32391265, 2020). "In the present study, we took advantage of this well characterized prospective cohort to assess the GH/IGF-1 axis in the sleep apnea-obesity comorbid couple." (PMID 32655494, 2020). "Among diabetes- and obesity-related factors, insulin and insulin-like growth factor 1 down-regulated 11β-HSD1 expression in fibroblasts and myeloid cells, while glucose, fatty acids, TNF-α and IL-1β did not affect it." (PMID 33260645, 2020). "Previous studies have shown that overweight/obesity and skeletal maturation are both influenced by these hormones, such as growth hormone (GH) concentration, insulin-like growth factor-1 (IGF-1), estrogens, and androgens." (PMID 32988365, 2020). "IGF-1 also play an important role on cancer, especially in obesity, a condition in which IGF-1 concentration in serum is elevated in a long-term manner, thus its effects are more related to growth factors, such as anti-apoptotic and mitogenic properties." (PMID 33371214, 2020). "The novelty of our work is to demonstrate that sleep apnea is a key player in the GH/IGF-1 axis dysfunction occurring in obesity." (PMID 32655494, 2020).
Obesity (continued). "Metabolic pathways most significantly enriched by the list of candidate genes include Relaxin Signaling, Leptin Signaling in Obesity, IGF-1 Signaling, PXR/RXR Activation and HIF1α Signaling pathways." (PMID 33499953, 2020). "The somatotropic axis has an important role in maintaining healthy conditions, and it is suppressed in obesity due to reduced GH and IGF-1 levels in the body." (PMID 32586279, 2020). "When subdivided on the basis of molecular subtype, IGF-1 expression didn't interact with obesity in RFS prediction." (PMID 32391265, 2020). "The first evidences of obesity-mediated pro-tumorigenic activity suggested the importance of altered systemic release of signaling molecules, including insulin, IGF-1, adipokines, cytokines and sexual hormones." (PMID 32659999, 2020). "After excluding interference by obesity, higher IGF-1 SDS (p = 0.009) and DHEAS SDS (p = 0.003) independently affect BA advancement." (PMID 32727432, 2020). "For example, IGF-1 is closely related to the pathological processes of obesity, cardiovascular disease, central nervous system disease, tumor development, and other diseases." (PMID 32793225, 2020). "Among obesity- and diabetes-related factors, insulin and insulin-like growth factor 1 (IGF-1) were identified as negative regulators of 11β-HSD1 expression and subsequent eGC production in skin." (PMID 33260645, 2020). "The altered GH–IGF-1 axis of obesity has important clinical implications and the decreased IGF-1 values of obesity are clinically relevant." (PMID 32806629, 2020). "The typical features of classical LS are short stature (−4 to −10 SDS below median height), typical face, obesity, high serum GH, and low to undetectable serum IGF1, unresponsive to the administration of exogenous GH." (PMID 33182502, 2020). "The effect of obesity on insulin and IGF-1-mediated responses in resistance vessels has been unclear." (PMID 30295509, 2019). "We have provided a number of insights into changes in the IR/IGF-1R/hybrid receptor system as obesity progresses, showing that after long-term obesity, IGF-1-mediated Akt phosphorylation is preserved in aorta and resistance vessels." (PMID 30295509, 2019). "We also show the intriguing finding that obesity blunts insulin-mediated resistance vessel relaxation and Akt phosphorylation, while IGF-1-mediated vasorelaxation and Akt phosphorylation remained intact." (PMID 30295509, 2019). "Reports regarding serum IGF-1 levels in obesity have shown contradictory results with both normal and decreased IGF-1 levels in obese subjects having been described." (PMID 31608009, 2019). "Our focus on endometrial cancer stems from the fact that this tumor is tightly correlated with obesity and, in particular, with the insulin/IGF1 signaling pathways." (PMID 31320996, 2019). "IGF-1 is a systemic growth-promoting factor, and its levels have been reported to be elevated in early-onset obesity." (PMID 31003943, 2019). "The alterations of GH/IGF-1 axis in obesity are characterized by the decrease in the half-life of GH along with a reduction in both frequency and amplitude of GH secretory bursts." (PMID 31527400, 2019). "Obesity-related genes were retrieved in the Digsee database and the top 15 obesity-related genes were selected as disease genes (Adipoq, Igf1, Fto, Hsd11b1, Tnf, Gh1, Mc4r, Lep, Pparg, Il6, Crp, Lepr, Pomc, Lpl, and Ghr1)." (PMID 31060494, 2019). "We analyzed serum IGF-1, leptin, and adiponectin levels to see the relationship and its possible role in the development of obesity." (PMID 31488172, 2019). "It should also be noted that IGF-1 levels are sensitive to age, gender, ethnic background, as well as degree of obesity." (PMID 29618342, 2018). "Pre-clinical studies have demonstrated a possible correlation between obesity-induced hormones (leptin and IGF-1) and PDAC chemoresistance via augmented epithelial-to-mesenchymal transformation (EMT)." (PMID 30366466, 2018).
Obesity (continued). "Obesity, due to physical inactivity and excess caloric intake, leads to high glucose, insulin, and insulin-like growth factor 1 (IGF-1) levels." (PMID 29214032, 2017). "The endocrine–metabolic regulatory axis comprising growth hormone (GH), insulin and IGF1, which is drastically altered under extreme metabolic conditions such as obesity, also plays relevant roles in the development, modulation and homeostasis of the PG." (PMID 28244645, 2017). "Obesity is characterized by hyposomatotropism, as documented by reduced GH responses to physiological and pharmacological stimuli, being serum IGF-1 levels generally normal-to-high." (PMID 28744309, 2017). "In this respect, it is noteworthy that low IGF-1 levels and altered GH-stimulated secretion in obesity seem to identify a subset of subjects with an increased cardiovascular risk." (PMID 28744309, 2017). "In conclusion, the present study shows that a not negligible subpopulation (25%) of patients with both FM and severe obesity has low IGF-1 SDS values, 12.5% failing also to normally respond to the GHRH plus arginine test." (PMID 28744309, 2017). "Molecular studies have shown that insulin, insulin-like growth factor (IGF-1) axis, adipokines, sex-steroid hormones, and chronic low-grade inflammation are the main pathways linking obesity and colorectal neoplasia, including CRAs and CRC." (PMID 29079785, 2017). "Evidence from animal studies also suggests that HFD-induced obesity results in higher concentrations of serum leptin, insulin, and insulin-like growth factor-1 (IGF-1), and facilitates colon tumor formation." (PMID 28170448, 2017). "High serum levels of insulin-like growth factor-1 (IGF-1) and low levels of insulin-like growth factor binding protein-3 (IGFBP-3) are associated with obesity, and obesity is associated with NALFD development." (PMID 28335515, 2017). "Our laboratory and others have shown that obesity increases the serum IGF-1 and lowers IGFBP-3 levels." (PMID 28335515, 2017). "Serum concentrations of insulin, insulin-like growth factor-1 (IGF-1), leptin, and adiponectin were measured as obesity-related phenotypic markers." (PMID 28170448, 2017). "Hyperinsulinism in patients with exogenous obesity leads to an increment in GV by increasing insulin-like growth factor 1 (IGF-1) production and bioavailability or showing a cross-reaction with IGF-1 receptors." (PMID 28418336, 2017). "Several mechanisms linking obesity to CRC have been proposed: obesity-related insulin resistance, hyperinsulinemia, sustained hyperglycemia, and a hyperinsulinemia-related increase of insulin-like growth factor-1." (PMID 28636624, 2017). "Generally, it should be noted that patients with lower levels of TT, cFT, DHEAS, and IGF-1 have a tendency to obesity and reduced muscle mass." (PMID 27274996, 2016). "Recently, studies demonstrate that obesity is strongly related to CRC, which is involved in several mechanisms, such as obesity-related insulin resistance, oxidative stress, adipocytokine production, and insulin-like growth factor-1 (IGF-1)." (PMID 27642602, 2016). "Previously, using global gene expression data from patients treated with neoadjuvant anastrozole, we showed that certain gene signatures such as IGF-1, MAPK and obesity were associated with poor response to therapy." (PMID 27246191, 2016). "To continue, IGF-1 and IGF-1 binding proteins will be linked to parameters of metabolic syndrome, diabetes, insulin resistance, and obesity." (PMID 26733412, 2016). "Berryman and colleagues revised IGF-1 actions on obesity, and concluded that this molecule possesses direct effects on muscle glucose uptake." (PMID 26733412, 2016). "Differently, levels of insulin and IGF-1 are commonly higher in subjects affected by age-related diseases or obesity than lean healthy subjects." (PMID 27899768, 2016).
Obesity (continued). "In the current study, we investigated leptin and IGF1 signaling due to our observation of increased obesity-related factors such as body weight, serum triglyceride and insulin, and peroxisome proliferator-activated receptor γ (PPARγ) after 56Fe radiation." (PMID 27558773, 2016). "But unlike the unequivocal effects of significantly lower GH observed in patients with obesity, there are some controversies about the relationship between obesity and IGF-1." (PMID 27343122, 2016). "The serum IGF-1 levels and IGF-1 SDS were significantly decreased in patients with any type of obesity related glomerular lesion (n = 69) compared with those without glomerular lesions (n = 11)." (PMID 27138941, 2016). "Upon observation of increased body weight and obesity-related factors, the current study dissected the leptin/IGF1 signaling axis previously unexplored in relation to heavy ion space radiation in mouse intestine and colon." (PMID 27558773, 2016). "Accordingly, we futher assessed the relationship between IGF-1SDS and obesity, and our study showed that the obese subjects had lower IGF-1 SDS compaed with control group." (PMID 27343122, 2016). "IGF-1 has been suggested as another potential player in the association between visceral obesity and EAC and its circulating levels are increased in obesity and other metabolic complications." (PMID 25857300, 2015). "Using 70 BC rGSSs, the method also predicted SN and SC BC prognostic genes from the tested obesity and IGF1 pathway GSSs." (PMID 26100469, 2015). "Patients with obesity, metabolic syndrome and diabetes showed significant lower plasma levels of IGF-1." (PMID 24498028, 2014). "Leptin, ghrelin, and insulin-like growth factor-1 are also known to be important mediators in acceleration of T-cell immunosenescence by obesity." (PMID 24651652, 2014). "We have shown that administering rhGH to female adolescents in physiologic doses is able to stabilize IGF-1 in obesity, a state characterized by relative GH insufficiency, without adversely affecting glucose tolerance." (PMID 25435886, 2014). "CR decreases, while diet- and genetically-induced obesity increases levels of insulin and bioavailable IGF-1." (PMID 24732966, 2014). "Calorie restriction (CR), an effective anti-obesity strategy with potent anticancer effects, has been shown to reduce serum levels of insulin, leptin, and IGF-1 and decrease the expression of protumorigenic cytokines." (PMID 24804677, 2014). "Given the structural and functional correlations between IGF1 and insulin, as well as the fact that both hormones employ identical signaling mediators, it is necessary to focus on the impact of obesity and diabetes on endometrial cancer." (PMID 24904527, 2014). "The aim of this study was to examine possible growth-promoting effects of native human insulin, insulin X10 and IGF-1, which are considered positive controls in vitro, in a short-term animal model of an obesity- and diabetes-relevant cancer." (PMID 24260289, 2013). "Obesity is typically accompanied by elevated circulating levels of insulin, bioavailable IGF-1 and leptin, as well as a series of pro-inflammatory cytokines." (PMID 23880059, 2013). "Similar to insulin, levels of IGF-1 correspond to energy status and are often elevated in obesity, possibly via hyperglycemia-induced suppression of IGFBPs synthesis and/or growth hormone receptor expression and IGF-1 synthesis." (PMID 23819063, 2013). "The aim of the study was to examine the possible tumor growth-promoting effect of treatment with HI, X10 and IGF-1 in a murine colon cancer allografts model (MC38 cells) established in mice with diet-induced obesity (DIO) and insulin resistance." (PMID 24260289, 2013). "There is evidence for deregulation of the growth hormone/insulin-like growth factor (IGF-1) signaling in obesity and an inverse relationship between total IGF-1 levels and BMI has been reported." (PMID 23446104, 2013).
Obesity (continued). "As circulating concentrations of insulin and IGF-1 rise with increasing obesity, the levels of the sex hormone-binding globulins decrease." (PMID 23983688, 2013). "Clinical manifestations consistent with GH insufficiency include short stature despite obesity, abnormal body composition, low insulin-like growth factor 1 (IGF-1) levels, and decreased GH secretion on provocative testing." (PMID 23962041, 2013). "Precocious adrenarche occurs in 15-30% of patients and is felt to be secondary to obesity or possibly increased adrenal exposure to insulin or IGF-1." (PMID 23962041, 2013). "The current paper focuses on the role of IR/IGF-1 signaling and IR/IGF-1 → FoxO-mediated transcription for the pathogenesis of obesity-associated dementia." (PMID 22654904, 2012). "Obesity and elevated insulin levels also induce more secretion of insulin like growth factor 1 (IGF-1), which stimulates cell growth and proliferation." (PMID 22829853, 2012). "Although IGF-1, adipocytokines, inflammation, and other obesity-related factors, as well as many cancers, have been individually associated with upregulation of TGF-β and other EMT pathway components, their combined interactions are poorly characterized." (PMID 23050968, 2012). "Among them, IGF1, SLC4A4, and WWOX were previously implicated as hypertension candidate genes in humans and mice and are primarily associated with obesity, glucose metabolism, and ion homeostasis, which are well-known mechanisms of blood pressure regulation." (PMID 22479346, 2012). "With obesity, the amount of bioavailable IGF-1 increases, possibly via hyperglycemia-induced suppression of IGFBP synthesis and/or hyperinsulinemia-induced promotion of hepatic growth hormone receptor expression and IGF-1 synthesis." (PMID 23050968, 2012). "In obesity, serum IGF-1 concentrations are usually normal but some authors reported reduced, or even elevated levels in obese children." (PMID 22899919, 2012). "We reported previously that RSV suppressed colon cancer cell proliferation and induced apoptosis even in the presence of IGF-1, a well-known growth factor elevated during obesity which has shown to enrich colon cancer stem cell populations." (PMID 21849056, 2011). "We have previously reported that at concentrations > 100 μM RSV suppressed colon cancer proliferation and up-regulated apoptosis even in the presence of IGF-1, elevated during obesity, and that has shown to enrich colon cancer stem cell populations." (PMID 21849056, 2011). "Clearly insulin and IGF-1 playmajor roles in cancer development and progression, especially in obesity and type 2diabetes." (PMID 23908801, 2011). "Our results indicate that resveratrol suppresses cell proliferation and induces apoptosis even when the cells are primed to proliferate with IGF-1, a mitogen that is highly bioavailable during obesity." (PMID 20504360, 2010). "In conclusion, we have shown resveratrol to suppress IGF-1 (IGF-1 levels are elevated during obesity) induced cell proliferation and elevate apoptosis in human colon cancer cells, and elucidated the mechanisms of action using IGF-1R siRNA." (PMID 20504360, 2010). "Insulin and IGF-1, often elevated in obesity, may further enhance central and peripheral HPG activation." (PMID 40933693, 2025). "Future longitudinal studies should investigate whether IGF-1 trajectories predict the progression of metabolic comorbidities in this population, which could help guide targeted interventions to mitigate obesity-related complications." (PMID 40379763, 2025). "The patient had high birth weight, large head circumference, obesity, central hypothyroidism, reduced attention, delayed puberty, macroorchidism, and some degree of GH deficiency followed by high IGF-1 concentrations, but no prolactin deficiency." (PMID 40162297, 2025).